CPEB1 (cytoplasmic polyadenylation element binding protein 1)
Diseases named in the same sentence as CPEB1 in open-access papers (continued):
Sharing a sentence is not in itself a finding about the gene and the disease.
endometrial cancer (5 papers, 2016 to 2024). Primary or metastatic malignant neoplasm involving the endometrium (mucous membrane that lines the endometrial cavity). "Our analysis revealed downregulation of CPEB1 expression in endometrial cancer, a finding supported by PCR, WB, and IF assays." (PMID 38994352, 2024). "Survival analyses from the Kaplan-Meier Plotter database revealed a significant decrease in OS of patients with endometrial carcinoma as the expression levels of CPEB1 and MYBL2 increased." (PMID 38994352, 2024). "Compared to the control group, the expression of MYBL2 was upregulated in endometrial carcinoma, whereas CPEB1 expression was downregulated." (PMID 38994352, 2024). "In endometrial cancer, miR-183 inhibits CPEB1 expression at the transcription and translation levels, and targets CPEB1 to induce EMT and promote tumorigenesis of EC cells." (PMID 32653017, 2020). "Two genes (CDC25A and IGF1R) were up-regulated (p = 0.04) in endometrial carcinoma, and CPEB1 was down-regulated (p = 0.05)." (PMID 27271671, 2016). "Among the significantly differentially expressed RBPs found in multiple cancer types, CPEB1 was differentially expressed in nine types of cancer; previous studies have reported its ability of promoting tumour migration in breast, liver and endometrial cancers." (PMID 32047888, 2020). "Besides, CPEB1 has been reported as a target gene of miR and participates in cell viability and apoptosis in endometrial cancer cell." (PMID 33228708, 2020). "Currently, there is a lack of research on CPEB1 in the context of endometrial cancer in the existing literature." (PMID 38994352, 2024).
hepatocellular carcinoma (5 papers, 2018 to 2024). A malignant tumor that arises from hepatocytes. "CPEB1 might also target the 3′-UTR of SIRT1 to suppress the growth of hepatic carcinoma." (PMID 33892791, 2021). "However, the involvement of CPEB1 in hepatocellular carcinoma (HCC) remains unclear." (PMID 30237545, 2018). "In hepatocellular carcinoma (HCC), Cpeb1 expression is downregulated." (PMID 34480525, 2022). "Additionally, studies have demonstrated that CPEB1 can directly target SIRT1, suppressing its translation and mediating cancer stemness in vitro and in vivo, suggesting its potential as a therapeutic target in hepatocellular carcinoma (HCC)." (PMID 38994352, 2024).
schizophrenia (4 papers, 2020 to 2023). A major psychotic disorder characterized by abnormalities in the perception or expression of reality. "Further studies indicate that ERVWE1 increases the expression of schizophrenia risk genes, such as Brain derived neurotrophic factor (BDNF) and Cytoplasmic polyadenylation element binding protein 1(CPEB1)." (PMID 37990254, 2023). "Of 1,183 genes that mapped to nominally significant DMPs, some were previously associated with BD or schizophrenia, including MLC1, ESR1, KCKN5, L1CAM, CPEB1 and GABBR2." (PMID 35922419, 2022). "Our study suggests the possibility that CPEB1 might similarly regulate genes that play a role in schizophrenia, possibly by interaction with FMRP." (PMID 31691811, 2020).
Azoospermia (3 papers, 2018 to 2022). Absence of any measurable level of sperm,whereby spermatozoa cannot be observed even after centrifugation of the semen pellet. "The ribosome loading itself is regulated by the CPE binding protein 1 (CPEB1) and deleted-in azoospermia such as (DAZL) binding to the cytoplasmic polyadenylation element (CPE) on the 3′ UTR of mRNA." (PMID 35884994, 2022). "Most of the mRNAs bound to translational ribosomes in mouse oocytes contain motifs for the RNA-binding proteins, CPEB1 and DAZL (deleted in azoospermia-like)." (PMID 36497033, 2022).
Insulin resistance (3 papers, 2012 to 2021). Increased resistance towards insulin, that is, diminished effectiveness of insulin in reducing blood glucose levels. "Concerning mRNAs, Slc1a5 was associated with hepatic glutamine uptake; Plp2 was able to increase ER-stress induced neuronal apoptosis while Cpeb1 was related with angiogenesis in chronic liver disease and involved in induction of insulin resistance." (PMID 27677588, 2016). "When fed on a high fat diet, WT and Cpeb1 KO mice were both obese, but only the KO animals displayed liver insulin resistance." (PMID 22253608, 2012). "In addition, this interaction has been associated to elevated IL-6 serum levels in the same study upon CPEB1 knock-out mice; this finding is known to be correlated to insulin resistance and even cancer (Fève and Bastard, 2009)." (PMID 34912244, 2021).
myeloma (3 papers, 2014 to 2023). "Moreover, the CPEB1 expression was reported to be significantly reduced in multiple myeloma cells, implying that CPEB1 may be related to myeloma progression." (PMID 36745802, 2023).
brain cancer (2 papers, 2020 to 2021). A primary or metastatic malignant neoplasm affecting the brain. "First, they showed that CPEB1 mRNA expression is reduced in reproductive-system and brain cancers." (PMID 33146632, 2020).
Infertility (2 papers, 2020 to 2023). "Given that change in timing of meiosis reentry and decreased translation of Ccnb1 in oocytes causes infertility, we tested whether a partial loss in CPEB1 expression in oocytes may affect fertility by mating CPEB1+/− female mice with wild-type male mice." (PMID 36697412, 2023).
neuroblastoma (2 papers, 2019 to 2023). Neuroblastoma (NB) is the most common solid, extracranial childhood tumor. "Moreover, an element that binds AU-rich binding factor 1 (AUF1) has been described, and a function for microRNA-dependent modulation of Cpeb1 has been described in neuroblastoma cells." (PMID 36697412, 2023).
pancreatic cancer (2 papers, 2017 to 2024). "In this study, we discovered CPEB1 as a key regulator controlling NRF2 proteostasis and ferroptosis susceptibility in pancreatic cancer, and established the clinical significance of CPEB1 in predicting therapeutic outcomes." (PMID 38904009, 2024). "In pancreatic cancer, low-expression of CPEB1 is associated with later TNM stage, and potentially worse survival." (PMID 38904009, 2024). "In support of the critical role of this signaling cascade in cancer therapy, CPEB1-deficient pancreatic cancer cells display higher resistance to ferroptosis-inducing agents than their CPEB1-normal counterparts in vitro and in vivo." (PMID 38904009, 2024). "During our study of ferroptosis in pancreatic cancer, we found that cytoplasmic polyadenylation element binding protein 1 (CPEB1) plays a critical role in controlling susceptibility to ferroptosis and is closely associated with clinical therapeutic outcomes." (PMID 38904009, 2024). "We then demonstrated that loss of CPEB1 in pancreatic cancer cells activated the expression of NRF2-target genes; and that overexpression of CPEB1 complementarily downregulated the expression of these genes." (PMID 38904009, 2024). "In the present study, we explored the role and underlying mechanism of CPEB1 in the regulation of ferroptosis in pancreatic cancer." (PMID 38904009, 2024). "To mimic CPEB1 deficiency in tumors, we constructed CPEB1-knockout (CPEB1-ko) pancreatic cancer cell lines derived from PANC-1 and JF-305 cells." (PMID 38904009, 2024). "In contrast to CPEB4, whose oncoprotein function in pancreatic cancer has been identified 36, the biological function and clinical significance of CPEB1 in pancreatic cancer are yet to be elucidated." (PMID 38904009, 2024). "All these results support the notion that the CPEB1-p62-KEAP1 axis functions as a critical regulatory pathway for controlling NRF2 homeostasis and susceptibility to ferroptosis in pancreatic cancer." (PMID 38904009, 2024). "The upregulation of p62 and NRF2 in CPEB1 deficient cells led us to hypothesize that the CPEB1-p62-KEAP1 axis regulates NRF2 proteostasis and ferroptosis in pancreatic cancer." (PMID 38904009, 2024). "However, based on our finding, detecting expression level of CPEB1 in pancreatic cancer is potentially informative for the clinical decisions when ferroptosis therapy is used in clinic." (PMID 38904009, 2024). "Hence, our results support the notion that CPEB1 is a potential prognosticator in pancreatic cancer." (PMID 38904009, 2024). "We also identify CPEB1 as a potential prognosticator of ferroptosis therapy in pancreatic cancer." (PMID 38904009, 2024). "However, the involvement of CPEB1 in pancreatic cancer and its role in cancer therapy remains unclear." (PMID 38904009, 2024). "To evaluate the clinical significance of CPEB1, p62 and NRF2 in pancreatic cancer, we collected tissue samples and clinical information from 90 patients with confirmed pancreatic ductal adenocarcinoma who underwent surgical resection." (PMID 38904009, 2024).
papilloma (2 papers, 2014 to 2016). A benign epithelial neoplasm that projects above the surrounding epithelial surface and consists of villous or arborescent outgrowths of fibrovascular stroma. "Moreover in carcinogenesis assay, papilloma formation was significantly faster in CPEB1 knockout than in wild-type animals." (PMID 25216517, 2014).
Premature ovarian insufficiency (2 papers, 2020 to 2025). Amenorrhea due to loss of ovarian function before the age of 40. "The polymorphism of CPEB1 gene might result in premature ovarian insufficiency." (PMID 40943102, 2025).
Primary amenorrhea (2 papers, 2020 to 2025). "One patient with primary amenorrhea was found to carry a heterozygous deletion of exons 8–12 of the CPEB1 gene." (PMID 32354341, 2020).
viral infection (2 papers, 2017 to 2022). "Previous studies have demonstrated that CPEB1 acts as a major regulator of stress granule (mRNA-ribonucleoprotein complex) formation, and modulates translational efficiency under stress conditions, including heat shock, hypoxia, and viral infection." (PMID 35496917, 2022). "Six optic nerves from six animals with Cpeb1 overexpression and six control optic nerves with GFP virus infection were analyzed 2 weeks after injury." (PMID 29379413, 2017).
(HCMV) infection (1 paper, 2025). "For instance, Human cytomegalovirus (HCMV) infection significantly up-regulates the expression of the cellular RNA-binding protein CPEB1, leading to an overall shortening of the 3′ untranslated region and a lengthening of poly(A) tails in host transcripts." (PMID 40580566, 2025).
Alzheimer disease (1 paper, 2023). A progressive, neurodegenerative disease characterized by loss of function and death of nerve cells in several areas of the brain leading to loss of cognitive function such as memory and language. "It has been reported that miRNA-455-5p/CPEB1 pathway mediated synaptic and memory deficits in Alzheimer’s Disease through targeting on AMPARs." (PMID 37187578, 2023).
diabetes (1 paper, 2022). "We provide insights into analyzing immune microenvironments and gene regulation features, indicating that both CPEB1 and COLEC12 are promising targets for immunotherapy of patients with diabetes who are diagnosed with BC." (PMID 36131924, 2022). "In-depth studies of the expression of CPEB1 and COLEC12 in fibroblasts and their roles in immune microenvironment interactions, particularly the complicated mechanisms connecting fibroblasts with immune cells, might provide novel strategies for BC immunotherapies in patients with diabetes." (PMID 36131924, 2022).
fragile X syndrome (1 paper, 2021). A genetic syndrome caused by mutations in the FMR1 gene which is responsible for the expression of the fragile X mental retardation 1 protein. "When modeling fragile X syndrome in mice (FMR1 knockout), mutations of the CPEB1 gene was found to reduce the pathological processes associated with the syndrome." (PMID 33789753, 2021).
Hodgkins lymphoma (1 paper, 2023). A heterogeneous group of malignant lymphoid neoplasms of B-cell origin characterized histologically by the presence of Hodgkin and Reed-Sternberg (HRS) cells in the vast majority of cases. "Previous study showed that in Hodgkin’s lymphoma-derived cell line, the CPEB1-coordinated alternative polyadenylation and splicing with translational regulation are involved in regulation of genes important for hematologic malignancy progression." (PMID 36745802, 2023).
knee osteoarthritis (1 paper, 2024). "Loading miR-25-3p into EVs has been shown to alleviate pyroptosis in chondrocytes in knee osteoarthritis by inhibiting the transcription of CPEB1." (PMID 38816719, 2024).
leukemia (1 paper, 2025). A malignant (clonal) hematologic disorder, involving hematopoietic stem cells and characterized by the presence of primitive or atypical myeloid or lymphoid cells in the bone marrow and the blood. "Genes that have been reported as abnormally methylated in leukemia, including CPEB1, BLK, FLT3, PAX5, EBF1, HDACs, IKZF1, RB, etc., were also detected in this study." (PMID 41226303, 2025). "As expected, several previously reported genes with abnormal methylation in leukemias such as CPEB1, BLK, FLT3, ZCCHC7, EBF1, HDACs, IKZF1, RB1, CDK6, DOCK5, DPP10, MUC4, JAKs, KIT, KRAS, LINC01013, MAD1L1, NOTCH1, and STATs, among others, were also detected." (PMID 41226303, 2025).
liver cancer (1 paper, 2018). An epithelial or non-epithelial malignant neoplasm that arises from the liver. "Immunohistochemical staining scores of CPEB1 in liver cancer were lower than those observed in the adjacent normal liver tissues." (PMID 30237545, 2018). "Immunohistochemical staining of a TMA showed that the expression of CPEB1 was weaker in liver cancer tissue than in non-cancerous tissue and primarily occurred in the cytoplasm of liver cancer tissues cells (tumor tissues, n = 68; peritumoral tissues, n = 60)." (PMID 30237545, 2018).
lung carcinoma (1 paper, 2023). "Studies have shown that human bone marrow-derived MSC-exos (BMSC-exos) can deliver miR-425 into lung cancer cells, inhibit CPEB1 expression, and promote lung cancer cell proliferation, invasion, and metastasis." (PMID 38071321, 2023).
metastatic melanoma (1 paper, 2022). A melanoma that has spread from its primary site to another anatomic site. "For example, with high levels of A-to-I editing in low metastatic melanoma but not in high metastatic melanoma, edited miR-455-5p lost the binding site of its downstream cancer suppressor protein CPEB1, which resulted in the suppression of melanoma growth and metastasis." (PMID 35898396, 2022).
ovarian carcinoma (1 paper, 2025). A malignant neoplasm originating from the surface ovarian epithelium. "A previous microRNA study reported that the CPEB1 gene is a target of miR-3646 and is downregulated in breast and ovarian cancers." (PMID 40943102, 2025).
ovarian failure (1 paper, 2020). "Our results combined with previous studies support the hypothesis that CPEB1 deficiency in humans might accelerate follicle atresia due to disrupted meiosis and oogenesis, thus resulting in ovarian failure at an earlier age, as is the case in POI." (PMID 32354341, 2020).
pancreatic ductal adenocarcinoma (1 paper, 2024). An infiltrating adenocarcinoma that arises from the epithelial cells of the pancreas. "Here we identified that cytoplasmic polyadenylation element binding protein 1 (CPEB1) regulates NRF2 proteostasis and susceptibility to ferroptosis in pancreatic ductal adenocarcinoma (PDAC)." (PMID 38904009, 2024).
Parkinson disease (1 paper, 2022). A progressive degenerative disorder of the central nervous system characterized by loss of dopamine producing neurons in the substantia nigra and the presence of Lewy bodies in the substantia nigra and locus coeruleus. "Interestingly, our data showed that CPEB1 knockdown significantly increased the mRNA levels of Pla2g6, which has been identified as the causative gene for an autosomal recessive form of Parkinson’s disease." (PMID 35496917, 2022).
periodontitis (1 paper, 2023). An acute or chronic inflammatory process that affects the tissues that surround and support the teeth. "Expression of known periodontitis risk genes CPEB1, ABCA1, and ATP6V1C1 was significantly repressed by hsa-miR-130a-3p, -144-3p, and -144-5p, respectively." (PMID 37822091, 2023). "The second most downregulated gene was periodontitis risk gene CPEB1 (cytoplasmic polyadenylation element binding protein 1) (log2FC = −1.5, Padj = 1.7 × 10−21), having the highest target score for hsa-miR-130a-3p binding." (PMID 37822091, 2023). "CPEB1 and CPEB4, another periodontitis risk gene, are essential for successful mitotic cell division and have sequential nonredundant functions." (PMID 37822091, 2023).
prostate carcinoma (1 paper, 2020). A carcinoma that arises from epithelial cells of the prostate gland. "A complementary prospective study with clinical prostate cancer samples has suggested that miR-145-5p and/or CPEB1 deficiencies are associated with TWIST1-dependent promotion of tumor growth and metastasis." (PMID 33227047, 2020). "We have discovered that miR-145-5p mediated control of TWIST1 in human prostate cancer cells is context-dependent, since it relies on the CPEB1 expression level." (PMID 33227047, 2020). "Strikingly, the function of miR-145-5p as a TWIST1 regulator was masked in 22Rv1 prostate carcinoma cells, which express high levels of CPEB1." (PMID 33227047, 2020). "To conclude, our work provides evidence that miR-145-5p and CPEB1 functionally overlap to control TWIST1 expression in prostate cancer cells by preventing EMT expression, cell migration, and stem cell properties." (PMID 33227047, 2020). "However, we discovered that the translational inhibitory effect of miR-145-5p on TWIST1 is lost in 22Rv1, another prostate cancer cell line that intrinsically expresses high levels of the CPEB1 cytoplasmic polyadenylation element binding protein." (PMID 33227047, 2020). "A preliminary prospective study using clinical samples suggests that reconsidering the relative status of miR-145-5p/TWIST1 and CPEB1 in the tumors of prostate cancer patients may bear prognostic value." (PMID 33227047, 2020).